Y_RNA (Y RNA )
Gene: Miscellaneous RNA gene on chromosome 21 (7,092,616 to 7,092,716, forward strand). Ensembl gene ENSG00000274046.
Homologues: Orthologues: chimpanzee Y_RNA (100% identical). Paralogues in human: Y_RNA (100% identical), Y_RNA (86% identical), RNY3 (85% identical), Y_RNA (85% identical), RNY3P1 (84% identical), Y_RNA (84% identical), RNY3P11 (83% identical), Y_RNA (83% identical), Y_RNA (82% identical), Y_RNA (81% identical), RNY3P3 (80% identical), Y_RNA (80% identical), and 95 more.